HOMEZ (homeobox and leucine zipper encoding)
Description:
May function as a transcriptional regulator.
Synonyms: KIAA1443
Tractability: PROTAC: UniProt records ubiquitination sites on it; ubiquitination databases record sites on it.
Gene: Protein-coding gene on chromosome 14 (23,272,422 to 23,299,796, reverse strand). Ensembl gene ENSG00000290292.
Subcellular location: Nucleus
Subcellular location (Human Protein Atlas): Nucleoli; Cytosol; Nucleoplasm
Gene Ontology:
Molecular function: protein binding; DNA-binding transcription factor activity, RNA polymerase II-specific; DNA binding
Biological process: regulation of transcription by RNA polymerase II
Cellular component: nucleolus; nucleoplasm; chromatin; nucleus
Homologues: Orthologues: chimpanzee HOMEZ (98% identical), macaque HOMEZ (97% identical), rabbit HOMEZ (89% identical), pig HOMEZ (88% identical), dog HOMEZ (87% identical), rat Homez (77% identical), mouse Homez (74% identical), tropical clawed frog homez (34% identical), zebrafish homeza (25% identical), guinea pig Homez (20% identical), zebrafish homezb (19% identical). Paralogues in human: ZHX3 (23% identical), ZHX1 (21% identical), ZHX2 (16% identical).
Diseases named in the same sentence as HOMEZ in open-access papers:
HOMEZ is named in the same sentence as 5 diseases in open-access papers, as found by Europe PMC text mining. Sharing a sentence is not in itself a finding about the gene and the disease. The quoted sentences say what the papers report.
congenital heart anomalies (1 paper, 2025). "On the other hand, it seems that the role of genes, such as GATA4, TBX5, NKX2-5, HOMEZ, PLAGL1, and CITED2, in heart development is significant, as numerous studies on knockout mice report that mutations in these genes are frequently associated with VSD or other congenital heart anomalies." (PMID 39466144, 2025).
HOMEZ also shares sentences with these, for which no sentence is quoted: cancer (1 paper); oral cancers (1); tumor (1); ventricular septal defect (1).